IL15 (interleukin 15)
Diseases named in the same sentence as IL15 in open-access papers (continued):
Sharing a sentence is not in itself a finding about the gene and the disease.
neuroblastoma (45 papers, 2012 to 2025). Neuroblastoma (NB) is the most common solid, extracranial childhood tumor. "As a result, scholars validated the tumor suppressive effect of IL-15 on PDX models, and they demonstrated that the replacement of IL-2 with IL-15 was associated with significant tumor regression in vivo, supporting clinical trials of IL-15 for pediatric neuroblastoma." (PMID 37081982, 2023). "IL-15 has been employed in autologous CAR-NKT cell therapies in the treatment of neuroblastoma, showing safety and improved in vivo performance of CAR-NKT cells." (PMID 39893165, 2025). "The clinical feasibility of this approach was demonstrated in the GINAKIT2 trial conducted by Heczey and colleagues, where autologous GD2 CAR-iNKT expressing IL-15 were manufactured for children with neuroblastoma." (PMID 40718496, 2025). "The GINAKIT2 trial (NCT03294954) evaluated autologous GD2-CAR-iNKT incorporating CD28/CD3ζ intracellular domains and IL-15 secretion in pediatric patients with relapsed or refractory neuroblastoma." (PMID 40718496, 2025). "IL-23-producing CAR T cells are particularly promising, able to regress neuroblastomas to a greater extent than IL-15- or IL-18-secreting CAR T cells." (PMID 39199630, 2024). "It should be also mentioned the trial of IL-15 GD2 CAR-T cell therapy for neuroblastoma and osteosarcoma (NCT03721068), which is underway." (PMID 39430751, 2024). "In neuroblastoma, Cy/Flu-induced lymphoid depletion increases the circulation level of the steady-state cytokine interleukin-15 (IL-15) and increases CAR-T-cell expansion by up to 3 logs." (PMID 36900151, 2023). "combined CAR T cells with an oncolytic virus armed with the chemokine RANTES and the cytokine IL15 in a neuroblastoma mouse model, and found that the intratumoral release of both RANTES and IL15 attracted CAR-T cells to improve CAR T cell influx." (PMID 36389701, 2022). "Nowadays, CAR-T cell targeted against GD2 and expressing IL-15 and iC9 is under evaluation in a clinical trial to treat patients with neuroblastoma (NCT03721068)." (PMID 39086964, 2022). "Use of this strain for neuroblastoma PDX allowed the study specifically to compare NK cell-mediated ADCC due to either IL-2 or IL-15 activated NK cells." (PMID 33808071, 2021). "This first-of-its-kind study of IL-15 in an established neuroblastoma PDX model provided compelling preclinical data that IL-15 should be evaluated in future clinical studies, at least to compare its tolerability against that of IL-2 in paediatric patients." (PMID 33808071, 2021). "These GD2.CD28.IL15 CAR NKT cells that target neuroblastoma indicated encouraging results in pre-clinical cancer models and were chosen for an initial clinical trial." (PMID 35008348, 2021). "Safety of autologous GD2-CAR.IL15 engineered iNKT cells is evaluated in patients with neuroblastoma (NCT03294954)." (PMID 33262761, 2020). "The cytokines IFN-γ, IL-2, IL-7, IL-12, IL-15, IL-18, IL-21, and IL-27, promoted neuroblastoma regression via enhancing the efficacy of effector cells, whereas VEGF, IL-6, and IL-10 induced neuroblastoma progression through their immunosuppressive activities." (PMID 33322408, 2020). "Transfection of miR-155 induced robust mRNA expression of IL-1β, IL-6, and IL-15 in neuroblastoma cells at 24 h after WNV NY99 infection." (PMID 31861621, 2019). "The persistence of NK cells and invariant NK T cells can be increased by constitutive secretion of IL-15, an approach being studied in clinical trials for children with neuroblastoma at Baylor College of Medicine (NCT03294954)." (PMID 30459759, 2018). "Given its pivotal role in the proliferation, survival, and activation of CD8+ T cells and NK cells, IL-15 has been identified as an antitumor cytokine in several cancers, including neuroblastoma, HCC, and breast and colorectal cancer." (PMID 29162948, 2017).
neuroblastoma (continued). "As naive NK cells were shown unable to eradicate neuroblastoma cells, we additionally used NK cells that were prior stimulated with IL-2 and IL-15, similar to NK cells used in cellular immunotherapy." (PMID 26452036, 2015). "Autologous GD2‐CAR iNKTs expressing IL‐15 induced a complete response in neuroblastoma." (PMID 41292193, 2025). "Preclinical research suggests that NKT cells transduced with the IL-15 gene could be a future adoptive cell therapy approach for neuroblastoma patients." (PMID 38791942, 2024). "Moreover, engineered NKT cells co-expressing both anti-GD2 CAR and IL-15 were used in a phase I study for children with relapsed or resistant neuroblastoma." (PMID 36830717, 2023). "RANTES and IL‐15 were previously shown to enhance CAR‐T‐cell migration in a neuroblastoma model." (PMID 38023712, 2023). "Expression of IL-15 as a reinforcement proliferative signal was also used in a neuroblastoma model." (PMID 35211124, 2022). "Based on these studies, the safety and efficacy of GD2-CAR NKT cells co-expressing IL-15 is currently being evaluated in pediatric patients with neuroblastoma, and an interim analysis of the first three patients found that infusion of CAR.IL15 NKT cells is safe and associated with clinical benefit." (PMID 34177932, 2021). "Similarly, our data demonstrated that transfection of miR-155 mimic induced robust mRNA expression of IL-1β, IL-6, and IL-15 in human neuroblastoma cells." (PMID 31861621, 2019). "Taking into consideration the promising activity of IL-15-expressing CAR-NKTs in patients with relapsed/refractory neuroblastoma, IL-12 engineering could represent the next step to manufacture long-term persisting innate cells for cancer immunotherapy in solid tumors." (PMID 38167707, 2024). "Since GD2.CAR-NKTs co-expressing IL-15 have been proved to be effective in pediatric patients with neuroblastoma, we compared GD2.CAR.IL15 NKTs with GD2.CAR(I)IL12 and GD2.CAR(I)IL12.TM in the neuroblastoma murine model at the lowest dose of CAR-NKTs." (PMID 38167707, 2024). "These IL-15 armored GD2-CAR NKT cells moved into clinical trials (ClinicalTrials.gov Identifier: NCT03294954) for treating children with relapsed neuroblastoma." (PMID 35806311, 2022). "Intratumor administration of Onc.Ad-IL15/RANTES increased the infiltration and persistence of GD2.CAR-T cells in a xenograft model of neuroblastoma resulting in significantly enhanced survival." (PMID 30298067, 2018). "An alternative system combines oncolytic viruses that secrete cytokines IL-15 and CCL5 with anti-GD2 CAR T cell therapy in xenograft models of neuroblastoma in order to increase T cell infiltration and persistence." (PMID 30459759, 2018). "IL-15 has also been integrated into other CARs to target other types of tumor; these include IL13Ra2-CAR and fibroblast growth factor-inducible 14 (Fn14-CAR) for glioblastoma and GD2-CAR for neuroblastoma." (PMID 39430751, 2024). "Moreover, it has been shown that co-expressing IL-15 and GD2 CAR potentiated the direct anti-neuroblastoma effect of Vα24-invariant natural killer T (NKT) cells." (PMID 34943898, 2021). "An Onc.Ad expressing both IL-15 and RANTES (Onc.Ad-IL15/RANTES) has demonstrated that combining both molecules can have a profound effect on adoptively transferred GD2.CAR-T cells, which have accomplished remission in patients with neuroblastoma." (PMID 30298067, 2018). "Stimulation of neuroblastoma cells with the IL2/IL15 cytokine mix alone did not induce MHC I upregulation." (PMID 26452036, 2015). "Immunogene therapy with IL-12- and IL-15-engineered neuroblastoma Neuro2a cells showed therapeutic efficacy by enhancement of CD8+ T-cell immunoresponses and potentiated the survivability of neuroblastoma-bearing syngenic mice." (PMID 21876694, 2012). "GD2-CAR IL-15 NKT cells could improve cell persistence in vitro, augment cell localization in tumor sites, and enhance tumor control compared to GD2-CAR NKT cells in mice bearing neuroblastoma." (PMID 37158883, 2023).
neuroblastoma (continued). "In neuroblastoma, GD2-specific CAR-T cells co-expressing IL-15 outperformed their IL-15-negative counterparts, exhibiting reduced exhaustion, improved in vivo persistence, complete tumor eradication, and protection upon tumor re-challenge in a metastatic xenograft model." (PMID 40771804, 2025).
colon carcinoma (42 papers, 2012 to 2025). "Low expression of Socs3 and Tcf3 have been associated with the occurrence and progression of CRC, while upregulation of Fas and Il15 is associated with malignant potential in colon cancer cells by promoting tumor motility and metastasis." (PMID 34843459, 2021). "After controlling for multiple comparisons, authors found that single nucleotide polymorphisms (SNPs) from four genes, IL3, IL6R, IL8, IL15, were associated with increased colon cancer risk." (PMID 34753514, 2021). "Interleukin-15 has been implicated as a promising cytokine for cancer immunotherapy, while folate receptor α (FRα) has been shown to be a potentially useful target for colon cancer therapy." (PMID 27438147, 2016). "After 27 days of the first treatment, plant-produced Pembrolizumab-IL-15Rα-IL-15 significantly inhibited colon cancer growth with an average final tumor volume of 103.11 ± 85.68 mm3." (PMID 39808627, 2025). "In both breast and colon cancer murine models, IL-15 promotes tumor destruction and reduces metastasis through T cell activation." (PMID 40032842, 2025). "Recently, it has been shown that multiple IT injections of IL-15 in MC38 colon carcinoma tumors suppressed tumor growth during the period of IL-15 administration, after which they rapidly grew." (PMID 39559362, 2024). "CXCR3+ NK-cell and CD8+ T-cell tumoral infiltration, directed by CXCL9 and CXCL10, can delay primary tumor growth in MC38 colon carcinoma and TC-1 epithelial carcinoma mouse models when treated with heterodimeric IL-15." (PMID 36030223, 2022). "In vitro assay indicated that F-PLP/pIL15 significantly increased IL15 secretion by colon cancer cells (CT26)." (PMID 35456655, 2022). "Recombinant IL-15 had been reported to evoke anti-tumor activity of adaptive and innate immune cells in colon cancer however, Short half-life and poor bioavailability limit the therapeutic potential of IL-15 systemic therapy." (PMID 36686835, 2022). "A study on the murine model of colon carcinoma reported the ability of IL-15 to improve the therapeutic index and antitumor efficacy of 5-FU." (PMID 33916844, 2021). "Prior studies have established the role of IL-15 in various tumor identities such as haematological malignancies, colon cancer or prostate cancer." (PMID 32929618, 2021). "Compared with non-targeted liposome (PLP), the targeted liposome (F-PLP) not only increased the transfection efficacy of the reporter gene, but also enhanced the expression and secretion of the IL15 gene in colon cancer cells in vitro." (PMID 27438147, 2016). "In mice with CT26 colon cancer, IL15 inhibited tumor growth and prolonged the survival rate, thus emerging as a candidate for colon cancer treatment." (PMID 27438147, 2016). "This is in contrast to another report that found that treatment with IL-15 in a metastatic model of colon carcinoma led to increased PD-1 expression on CD8 T cells in the spleen." (PMID 25879689, 2015). "In the present study, FMT considerably increased the IL-15 expression in the colonic cancer area." (PMID 40431182, 2025). "Similarly, IL-15-based agonists enhanced the NK cell response to Cetuximab-treated squamous cell carcinoma of head and neck and colon cancer and to Rituximab-treated B cell lymphoma cell lines." (PMID 36300122, 2022). "Interestingly, a recent report revealed that extracellular vesicles derived from IL-12/15/18-stimulated NK-92 cells showed higher ability to induce apoptosis in HCT116 colon cancer cell spheroids in comparison with IL-15-stimulated controls." (PMID 35603208, 2022). "A vesicular stomatitis virus (VSV) encoding IL-15 was not superior to parental VSV in a subcutaneous CT26 colon cancer model, but was more effective in preventing lung colonization, which was associated with increased peripheral NK cell counts." (PMID 31623390, 2019).
colon carcinoma (continued). "However, an increased anti-tumor efficacy was observed upon treatment with Rituximab and N-803 in immunodeficient mice reconstituted with human NK cells or with Cetuximab and Sushi IL-15-Apo protein in human PBMC reconstituted mice bearing HT-29 colon cancer xenografts." (PMID 36300122, 2022). "De Vries and colleagues FACS sorted between 168 and 3775 γδ T cells derived from colon cancer tissue which were expanded for 3-4 weeks using PHA, IL-2 and IL-15, reaching a 2000 to 170.000-fold expansion." (PMID 38426099, 2024). "To address checkpoints, we administered IL-15 in combination with antibodies to PD-L1 and cytotoxic lymphocyte antigen-4 (CTLA-4) in the CT26 and MC38 colon carcinoma and TRAMP-C2 prostatic cancer syngeneic tumor models." (PMID 32508818, 2020). "Herein, we developed F-PLP/pIL15, a FRα-targeted lipoplex loading recombinant interleukin-15 plasmid (pIL15) and studied its antitumor effects in vivo using a CT26 colon cancer mouse model." (PMID 27438147, 2016). "The IL15 expressed by colon cancer cells is only secreted in a complex with its receptor (IL15/IL15R); thus, an ELISA kit measuring IL15/IL15R was used to determine IL15 expression levels." (PMID 27438147, 2016). "Of these immunomodulators, interleukin-15 (IL15), a potent pro-inflammatory cytokine, has emerged as a candidate immunomodulator for the treatment of colon cancer." (PMID 27438147, 2016). "We previously showed that IL-15:IL15Rα-secreting cell-based cancer vaccine surpassed those expressing IL-15 alone for eliminating tumors, preventing tumor recurrence and enhancing overall survival of tumor-bearing mice in CT26 colon cancer cells." (PMID 34439192, 2021). "Although IL15 alone is not involved in any major cancer signaling pathways, the IL15+IL15R complex can suppress CT26 colon cancer cells through NK cells, which is consistent with the findings on the upregulation of IL15 by intensive aerobic exercise in the current study." (PMID 35801156, 2022). "Interestingly, only IL-15 trans-presented via its receptor IL-15α, but not soluble IL-15, could efficiently stimulate the cytotoxic function of immune effectors against colon carcinoma cells." (PMID 33916844, 2021).
glioma (42 papers, 2013 to 2025). A benign or malignant brain and spinal cord tumor that arises from glial cells (astrocytes, oligodendrocytes, ependymal cells). "In this study, we explored the potential use of microglia engineered to express IL-15 upon infection with a recombinant adeno-associated virus serotype 2 (rAAV2) carrying IL-15 (rAAV2-IL-15), to simulate the effect of EE on glioma." (PMID 34552593, 2021). "Higher levels of IL-15 and IL-16 were independently associated with lower glioma risks (Ptrend = 0.002 and Ptrend = 0.001); both associations were more pronounced in individuals with prior immune conditions (Pheterogeneity = 0.0009 and Pheterogeneity = 0.031)." (PMID 30297770, 2018). "Associations with pre-diagnostic levels of IL-15 and IL-16 and their modification by diagnosis of immune-related conditions support the importance of immune alterations in glioma aetiology years before diagnosis." (PMID 30297770, 2018). "The lack of a main effect of immune-related conditions in our study does not preclude a role for these conditions in the aetiology of glioma insofar as a prior diagnosis of an immune-related condition significantly modified the associations of glioma risk with IL-15 and IL-16." (PMID 30297770, 2018). "However, IL-15-modified CAR T-cells were still susceptible to antigen escape as gliomas that recurred after 40 days following CAR T-cell treatment, suggesting that targeting multiple antigens may still be necessary in addition to providing cytokine support." (PMID 38136398, 2023). "When loaded with TMZ and interleukin-15 (IL-15), cRGD-modified NKCNPs promoted dendritic cell maturation and NK cell activation, leading to significant tumor reduction and extended survival in glioma models." (PMID 40624508, 2025). "TA-MSCs from tumors like osteosarcoma, breast cancer, ameloblastoma, gastric cancer, glioma, and ovarian carcinoma, promote tumor cell stemness by releasing factors such as IL-6, IL-15, R-spondin, exosomal miR-1587, BMP, and LIF." (PMID 40676710, 2025). "In the orthotopic glioma xenograft mouse model, IL13Rα2 CAR T cells that were also designed to express IL-15 exhibited elevated anti-glioma activity, enhanced persistence, and considerably longer survival than the control." (PMID 36721153, 2023). "Intracranial tumors of glioma-bearing mice were collected; we found significant reductions in tumor volumes after the addition of Ad5-Ki67/IL-15 treatment." (PMID 35765095, 2022). "IL-15 co-expression was also used in a model of IL-13Rα2-positive glioma (IL-13Rα2-CAR.IL-15 T cells) and results showed better in vivo persistence and greater antiglioma activity." (PMID 35211124, 2022). "Our investigation revealed that oncolytic Ad5-Ki67/IL-15 downregulate PD-L1 expression in glioma with the presence of GA-MSCs." (PMID 35765095, 2022). "To investigate the efficacy of IL-15 produced by engineered microglia against glioma, we intranasally delivered these cells every 3 days starting 7 days after GL261 glioma cell transplantation in mice." (PMID 34552593, 2021). "Altogether, our data support the key role of microglia-derived IL-15 in regulating the glioma microenvironment and boosting immune cell activation." (PMID 34552593, 2021). "In this paper, we investigated the possible therapeutic efficacy of the adoptive transfer of microglia, modified with the rAAV vector carrying IL-15, to mimic the EE effects on glioma." (PMID 34552593, 2021). "To mimic the effect of EE on glioma, we investigated the potential of creating engineered microglia as the source of IL-15 in glioma." (PMID 34552593, 2021). "Altogether, our results demonstrated that i.n. delivery of IL-15-engineered microglia is able to reproduce the effect of EE on NK cell and tumor volume in glioma mouse models." (PMID 34552593, 2021). "One key molecule produced by microglial cells upon EE exposure is IL-15, which modifies the tumor microenvironment boosting the immune system to counteract glioma growth." (PMID 34552593, 2021).